TIGIT (T cell immunoreceptor with Ig and ITIM domains)
Diseases named in the same sentence as TIGIT in open-access papers (continued):
Sharing a sentence is not in itself a finding about the gene and the disease.
cancer (601 papers, 2015 to 2026). A tumor composed of atypical neoplastic, often pleomorphic cells that invade other tissues. "TIGIT is associated with the exhaustion of NK cells in vivo and is observed in individuals with various types of cancer." (PMID 40417700, 2025). "A pivotal pathogenic factor, the autotransporter adhesin Fap2, facilitates association to cancer and immune cells via the receptors Gal-GalNAc and TIGIT, respectively, leading to deactivation of immune cells." (PMID 40883327, 2025). "CD155, as the primary binding partner of TIGIT, predominantly initiates suppressive signals in the immune system and is linked with unfavorable outcomes in cancer cases." (PMID 40777027, 2025). "The levels of various IC receptors, including TIGIT and PD-1, is strongly associated with NK cell functional exhaustion in cancer patients." (PMID 40463500, 2025). "The expression of TIGIT is associated with T cell exhaustion in cancer and chronic infections, contributing to immune evasion by tumors." (PMID 39064019, 2024). "PD-1+ TIGIT+ Cd8 T cells are associated with worse prognosis in cancer, and the relationship between this dual immune checkpoint expressing T cell phenotype and the PDAC TLS have yet to be elucidated." (PMID 38361928, 2024). "Although ST6GALNAC1 shares a weak association with TIGIT, the sialyltransferase also shares significant expression with TIGIT, another immune checkpoint associated with cancer progression." (PMID 39348343, 2024). "It has been proven that TIGIT is associated with T-cell exhaustion and immunosuppressive effects across all stages of the cancer immunity cycle." (PMID 37291608, 2023). "Combined with the results of this study, it is plausible that TIGIT kills cancer cells in the low-risk group by reducing DC-triggered T-cell initiation, leading to immunotherapeutic benefits for patients in the low-risk group." (PMID 37187896, 2023). "TIGIT expression appears to be associated with advanced disease status and poor clinical outcomes in several cancers." (PMID 35625835, 2022). "In humans, increased TIGIT expression in cancer is associated with worse disease outcomes and TIGIT blockade and siRNA knockdown in T cells restores their effector functions." (PMID 35273617, 2022). "The DNAM-1 receptor and its inhibitory counterparts, TIGIT and Tactile, have been implicated in cancer of multiple histotypes." (PMID 34956230, 2021). "TIGIT is associated with human cancers and expressed on NK and lymphoid cell populations (activated and memory T cells, and a subset of Treg)." (PMID 32039024, 2019). "The observed increase in mutation load in the low-risk group, alongside the elevated expression of immune checkpoint markers such as CD24, CD28, CTLA-4, and TIGIT in the high-risk group, underscores the complex interplay between genetic mutations and immune escape mechanisms in cancer development." (PMID 40510341, 2025). "Moreover, protein-protein interaction network analysis demonstrated that cancer cells expressing NECTIN2 were associated with T cell function through the coinhibitory receptor TIGIT, which promotes T cell dysfunction for immune evasion." (PMID 40371640, 2025). "As neutrophil infiltration denotes host inflammation, an important hallmark of cancer, TIGIT methylation might have significance in cancer immunology." (PMID 40076932, 2025). "TIGIT activation in cancer may address Treg deficiencies and reduce inflammatory cytokine production." (PMID 40567374, 2025). "TIGIT has been associated with NK cell exhaustion in vivo and in individuals with various cancers." (PMID 38229100, 2024). "A T cell immunoreceptor with Ig and ITIM domains (TIGIT) has emerged as a compelling negative regulator of cytotoxic lymphocytes and represents an attractive target for cancer therapy, potentially offering a reduced risk of irAEs compared to anti-PD-1 or anti-CTLA-4 monoclonal antibodies (mAbs)." (PMID 37569880, 2023).
cancer (continued). "The results of the association between IFN-γ score and ICG indicated that the IFN-γ scores of virtually all of the different cancers that were investigated had a positive association with the expression of TIGIT, IDO1, ICOS, CD86, CTLA4, HAVCR2, PDCD1LG2, and CD48." (PMID 37646041, 2023). "Overexpression of TIGIT was associated with poor prognosis in many cancers." (PMID 37427115, 2023). "Thus, our results revealed functional mechanisms of KIR2DL5-mediated NK cell immune evasion, demonstrated blockade of the KIR2DL5/PVR axis as a therapy for human cancers, and provided an underlying mechanism for the clinical failure of anti-TIGIT therapies." (PMID 36377656, 2022). "TMB and MSI were also associated with TIGIT upregulation in diverse kinds of cancers." (PMID 36211383, 2022). "However, further studies are needed to elucidate the underlying mechanisms for the co-expression of TIGIT and PD-1 in cancer." (PMID 34638729, 2021). "Indeed, overexpression of TIGIT has been associated with poor prognosis in numerous cancers including bladder, gastric, lung adenocarcinoma and HCC." (PMID 33401460, 2021). "TIGIT has been associated with NK-cell exhaustion in cancer patients." (PMID 34943606, 2021). "Particularly, CD48, HAVCR2, LAG3, and TIGIT were identified as novel immunotherapeutic targets of several cancers, suggesting that the low-risk OS patients might benefit from their candidate inhibitors." (PMID 32908905, 2020). "Only recently, it was suggested that anti-TIGIT drugs might be associated with less autoimmune-like toxicity, making TIGIT an appealing target for new cancer immunotherapies." (PMID 30733837, 2019). "Our novel observation that TIGIT is highly expressed on senescent T cells led us to speculate that TIGIT contributes to the functional defect of these T cells and subsequently increases the susceptibility to infection or cancer." (PMID 29349889, 2018). "Thus, we hypothesized that the potential interaction of TIGIT/CD155 on cancer-associated DCs might be important in the regulation of immune function in cancer." (PMID 35794399, 2023). "Similarly, TIGIT upregulation in the elderly may lead to age‐related T‐cell dysfunction and the loss of immune surveillance for cancer." (PMID 29349889, 2018). "In this study, we investigated strategies to further potentiate the co-blockade of PD-L1 and TIGIT for cancer immunotherapy." (PMID 41613119, 2026). "The concurrent upregulation of PD‐1 and TIGIT is consistent with findings from chronic infection and cancer models, where sustained antigen exposure drives functional exhaustion." (PMID 40960283, 2026). "In humans, CD155 overexpression is associated with resistance to ICI treatment in NSCLC, and TIGIT expression is significantly overexpressed in many cancers, particularly NSCLC." (PMID 40075753, 2025). "This duality highlights the complex roles of PD-1 and TIGIT in modulating immune responses in cancer." (PMID 41300994, 2025). "Our findings support a model in which RNA modifications, particularly m6A, act as fine-tuners of CD70, CD80, and TIGIT expression across multiple cancer types." (PMID 40565233, 2025). "Accordingly, targeting TIGIT is considered a promising therapeutic approach in cancer immunopathology." (PMID 40567374, 2025). "Recently, the IC axis involving the poliovirus receptor (PVR, CD155), poliovirus receptor-like 2 (PVRL2, CD112), and T cell immunoreceptor with Ig and ITIM domains (TIGIT) has emerged as a promising target for cancer immunotherapy." (PMID 40317320, 2025). "T cell immunoreceptor with Ig and ITIM domains (TIGIT) is a promising new target in cancer immunotherapy that is currently under investigation." (PMID 39939955, 2025). "The immunoglobulin-associated receptor family (TIGIT, CTLA4, CD274, and BTLA) have inhibitory effects on T cell function and have been used as a part of immunomodulatory strategy for treating cancers." (PMID 40173324, 2025).
cancer (continued). "Increasing evidence supports its function as a modulator of key immune regulatory molecules, including CD70, CD80, and TIGIT, influencing cancer immune evasion." (PMID 40565233, 2025). "Different studies have revealed the emerging role of TIGIT in cancer immunotherapy, either as monotherapy or dual immune checkpoint inhibition (ICI) therapy." (PMID 40565233, 2025). "T cell immunoreceptor with immunoglobulin and immunoreceptor tyrosine-based inhibitory motif domains (TIGIT) is an immune checkpoint that was recently highlighted as a candidate target in cancer immunotherapy." (PMID 40526725, 2025). "Among these lC, the poliovirus receptor/poliovirus receptor-like 2 protein (PVR/PVRL2)-TIGIT axis was discovered as potential target for various cancers." (PMID 40317320, 2025). "It has been reported that TIGIT and PD-1 are upregulated in CRC with mismatch repair deficiency, with higher expression observed in cancer tissues than in adjacent normal mucosa." (PMID 40567374, 2025). "TIGIT, an immunological checkpoint receptor, suppresses T cell activation and promotes immune evasion in various cancers." (PMID 40567374, 2025). "Studies have also shown that the level of TIGIT is elevated in both the peripheral blood cells of healthy individuals and cancer patients, suggesting its role in suppressing immune responses in the context of cancer." (PMID 40574024, 2025). "TIGIT overexpression and high infiltration of CD8+ TIGIT+ T cells have been linked to an unfavorable prognosis in numerous cancer types." (PMID 40075727, 2025). "Recent clinical trials on TIGIT blockade in cancer have been initiated predominantly in combination treatments." (PMID 40003864, 2025). "It interacts with immune checkpoints like TIGIT to suppress T-cell activity, reducing the immune system's ability to target cancer cells." (PMID 40369504, 2025). "Consistent with murine studies, well-known Tex genes (CTLA4, LAG3, HAVCR2 (gene encoding Tim-3), PDCD1, TIGIT, TOX) were among the most prominently represented in Tex from human cancers." (PMID 40236693, 2025). "Our research shows that PIEZO1 expression is positively correlated with key immune checkpoints, including CD274 (PD-L1), CTLA4, LAG3, PDCD1 (PD-1), PDCD1LG2 (PD-L2), and TIGIT across various cancer types." (PMID 40977743, 2025). "TIGIT expression is elevated in CD8+ T cells of several malignant tumors, and a high TIGIT/DNAM1 ratio in Treg correlates with poor prognosis after blockade of the PD-1 and/or CTLA-4 pathways." (PMID 40038799, 2025). "Emerging evidence highlights the synergistic potential of combining anti-TIGIT antibodies with LAG-3 or CTLA-4 inhibitors in cancer immunotherapy." (PMID 40567374, 2025). "TIGIT, LAG3, PDCD1, and CXCL13 were highly associated with different stages of cancers, especially in KIRC and THCA." (PMID 40076932, 2025). "TIGIT is also a promising, novel molecular target in cancer immunotherapy, which is also due to its synergistic action with other ICIs." (PMID 40574024, 2025). "Additional studies have confirmed that TIGIT gene knockout enhances NK cell cytotoxicity against diverse cancer cell lines, including spheroids." (PMID 40463500, 2025). "Multiple studies have demonstrated the efficacy of anti-TIGIT therapy in various mouse models and human cancer patients, with promising results even in advanced or metastatic solid tumors." (PMID 39939322, 2025). "The use of antibodies against PD‐1, CTLA4, and TIGIT has been tested in clinical trials for treating cancer patients." (PMID 40100045, 2025). "The studies reviewed highlight the significant potential of TIGIT as a therapeutic target in cancer immunotherapy." (PMID 40567374, 2025). "Overall, TIGIT suppresses cancer immunity by directly inhibiting CD8+ T cells and enhancing Treg‐mediated inhibition." (PMID 40415479, 2025). "Several ongoing studies are investigating the potential role of anti-TIGIT therapy in the earlier stages of various cancer types." (PMID 39847233, 2025).
cancer (continued). "These two drugs target the TIGIT and PD-L1 immune checkpoints, respectively, and influence the immune microenvironment and metabolic state of cancer cells by regulating the activity and function of immune cells." (PMID 39744225, 2025). "Other immune checkpoints, such as LAG-3, TIM-3, and TIGIT, are under exploration as cancer immunotherapy and can possibly be integrated into liposomal delivery systems for more efficient cancer targeting." (PMID 40872479, 2025). "The exploration of tiragolumab, a monoclonal antibody targeting TIGIT, represents a significant advancement in cancer immunotherapy, particularly within the context of the immunosuppressive TME." (PMID 40567374, 2025). "TIGIT is a next-generation immune checkpoint molecule that is potentially valuable in cancer immunotherapy." (PMID 40526725, 2025). "In this case, anti-CTLA-4 and anti-TIGIT therapies not only led to a reduction in the percentage of mesenchymal EpCAM− cancer cells but also induced the enrichment of epithelial EpCAM+ cancer cells." (PMID 38914547, 2024). "TIGIT not only influences the survival and exhaustion of NK cells, as observed in animal models and cancer patients, but it also actively mediates T cell depletion." (PMID 38229100, 2024). "We discovered that JAK2-mutated cancers displayed upregulated expression of immune checkpoint molecules (such as PDCD1, CD274, CTLA4, and TIGIT) compared with JAK2-wild tumors." (PMID 38200372, 2024). "Anti-TIGIT alone and in combination with anti-PD-1 agents have been tested for cancer immunotherapy." (PMID 38229100, 2024). "TIGIT is associated with NK-cell exhaustion and TIGIT blockade augmented NK-cell activation and CD8+ T-cell effector function in murine models of cancer." (PMID 38223411, 2024). "T cell immunoreceptor with immunoglobulin and ITIM domain (TIGIT) contributes to suppress the immune response against malignancies through multiple routes." (PMID 38807601, 2024). "LAG-3, TIM-3 and TIGIT biology and its role for treatment of cancers has been reviewed in detail elsewhere." (PMID 38322418, 2024). "The CD155/TIGIT axis has attracted considerable interest as an emerging immune checkpoint with potential applications in cancer immunotherapy." (PMID 38216949, 2024). "Accumulating evidence have proved that TIGIT are involved in the development of autoimmunity, cancer and chronic infection." (PMID 38545097, 2024). "Many studies have demonstrated that dysfunctional CD8 T cells in cancer are characterised by high expression levels of inhibitory receptors, including PD-1, TIM-3, LAG-3, and TIGIT, which are positively associated with T cell exhaustion." (PMID 39676870, 2024). "Different studies have shown that TIGIT is overexpressed across different cancer types, such as KIRP, KICH, LUAD, and COAD." (PMID 39064019, 2024). "TIGIT, an inhibitory receptor expressed on lymphocytes, is a crucial IC that can impede every step of cancer immunity." (PMID 38711501, 2024). "Accordingly, the anti-PD-L1/TIGIT combination is the most effective strategy for blocking the growth of cSCCs that contain both epithelial and mesenchymal cancer cells." (PMID 38914547, 2024). "TIGIT blockade therapies rely on activated T and NK cells; however, the interaction of cancer cells, stromal cells and immune cells in the complex TME promotes chronic inflammation and immunosuppression." (PMID 39771968, 2024). "TIGIT is expressed on T cells, regulatory T cells, and NK cells, and activates an immunoregulatory network on antigen-presenting and cancer cells." (PMID 39275127, 2024). "The field of cancer immunotherapy is progressively shifting its attention towards TIGIT, which is a suppressive receptor found on lymphocytes." (PMID 39623397, 2024). "TIGIT represents a promising target in cancer immunotherapy, particularly in combination with a PD-1 inhibitor." (PMID 38893211, 2024).
cancer (continued). "Several monoclonal antibodies have been synthesized to target TIGIT, with clinical trials on TIGIT inhibition in several cancer types underway, but further investigation for activity against metastatic UM is needed." (PMID 39026970, 2024). "That means that TIGIT activates the apoptosis pathway in 47% of the selected cancers, EMT pathway in 22%, and ER in 31% of them." (PMID 39064019, 2024). "We observed a transition from CD8+ T cells expressing CD226 and CD96 to those expressing TIGIT once these cells had infiltrated into the cancer nest, consequently disrupting the immune equilibrium between the three receptors observed in healthy lungs." (PMID 38279870, 2024). "Anti-TIGIT therapy has been explored as an emerging targetable inhibitory immune checkpoint molecule for cancer immunotherapy." (PMID 38724599, 2024). "This differentiation is associated with poor responses to immunotherapy in cancer patients and the upregulated expression of “exhaustion” cell markers such as PD-1, TIM-3, LAG-3, TIGIT, and CTLA-4." (PMID 38727261, 2024). "T‐cell immunoglobulin and immunoreceptor tyrosine‐based inhibitory motif domain (TIGIT) is an immune checkpoint molecule that suppresses CD8+ T‐cell function in cancer." (PMID 38279870, 2024). "Nonetheless, it’s noteworthy that the interaction between CD155 and TIGIT plays a role in conferring resistance to PD-1 blockade within the context of cancer." (PMID 38375475, 2024). "In the past two decades, emerging studies confirmed that the blockade of ICBs (PD-1, PD-L1, CTLA4, TIM-3, TIGIT etc.)has rapidly become the most promising anti-cancer strategies for multiple types of cancer, including GC." (PMID 39074262, 2024). "Variations in TIGIT expression not only differ from cancer to cancer but also due to the presence of malignant cells in the lymph nodes, which has also been observed for TIM-3." (PMID 38893211, 2024). "These agents work by blocking the interactions of PD-1, CTLA-4, NKG2A, TIGIT, etc. with their ligands on cancer cells, releasing the “brakes” of T and NK cells to eliminate cancer cells more efficiently, promoting long-lasting anti-tumor responses." (PMID 39682686, 2024). "By blocking the CD155/TIGIT axis, the immune response can be enhanced and promote the elimination of cancer cells." (PMID 38627665, 2024). "Consistent with prior investigations on TIGIT expression and cancer prognosis, our Kaplan–Meier curve analysis demonstrated that patients with high TIGIT expression had shorter RFS and OS compared to those with low TIGIT expression." (PMID 39540362, 2024). "The EPHA3-EFNA1 axis was expressed only in cancer-associated fibroblast (CAF) and melanocytes of PM, and the TIGIT-NECTIN2 axis was expressed in both AM subtypes of T/NK cells and melanocytes." (PMID 38528036, 2024). "It has also been identified that TIGIT is correlated with T cell exhaustion and immunosuppressive effects in different cancer types." (PMID 39064019, 2024). "NECTIN2 (CD122) is overexpressed in various cancers, and TIGIT is commonly expressed in most Tregs in humans as a co‐inhibitory molecule." (PMID 39601163, 2024). "Due to the blocking mechanisms of anti-LAG-3 and anti-TIGIT, it is assumed that simultaneous blockade of LAG-3 and TIGIT would be a novel strategy for cancer immunotherapy." (PMID 38724599, 2024). "TIGIT is reported to be highly expressed on dysfunctional or exhausted T cells in chronic diseases such as chronic viral infection and cancer." (PMID 38540243, 2024). "Increasing evidence indicates that the CD155/TIGIT signaling pathway assumes a pivotal role in modulating the immune microenvironment across various cancer types." (PMID 38216949, 2024). "The advantages and disadvantages of targeting TIGIT using mAbs, bispecific and tri-specific antibodies (bsAbs and tsAbs), peptides, and compounds, in addition to potential combination therapies of anti-TIGIT with anti-PD-1 or cancer vaccines, are addressed." (PMID 39771968, 2024).